CTLA4 (cytotoxic T-lymphocyte associated protein 4)
Diseases named in the same sentence as CTLA4 in open-access papers (continued):
Sharing a sentence is not in itself a finding about the gene and the disease.
meningitis (13 papers, 2018 to 2025). A disorder characterized by acute inflammation of the meninges of the brain and/or spinal cord. "The reintroduction of ipilimumab has remained controversial because anti-CTLA4 agents are associated with a higher rate of meningitis and irAEs." (PMID 35416575, 2022). "Meningitis (0.15% of patients in their cohort) was preferentially associated with the use of anti-CTLA-4 agents." (PMID 35416575, 2022). "We have previously shown that VZV reactivation in patients with herpes zoster or meningitis leads to an upregulation of CTLA-4 on VZV-specific T-cells, which normalized after resolution of symptoms." (PMID 39265505, 2024). "It is noteworthy that polyradiculoneuropathy and meningitis were also more frequently observed in patients with anti-CTLA4 treatments, indicating that the type of ICI may also influence the type of clinical presentation and therefore the outcomes." (PMID 37389303, 2023). "We have previously shown that patients with herpes zoster and VZV-associated meningitis show increased levels of VZV-specific T cells with limited ability to produce cytokines and with increased expression levels of markers of functional anergy such as CTLA-4 or PD-1." (PMID 30413189, 2018).
rectal cancer (13 papers, 2017 to 2025). A primary or metastatic malignant neoplasm that affects the rectum. "Immune checkpoint inhibitors (ICIs), particularly inhibitors targeting programmed cell death protein-1 (PD-1) and cytotoxic T lymphocyte-associated protein-4 (CTLA-4), have shown promising therapeutic potential for patients with locally advanced rectal cancer (LARC) and metastatic CRC." (PMID 40552298, 2025). "In a murine model of rectal cancer RT combined with CTLA-4 inhibition reduced formation of metastases." (PMID 38623751, 2024). "Given the growing interest in radiogenomics, it is possible that future studies will investigate the relationship between radiomic features and specific immune-related genes, such as CTLA-4, in rectal cancer." (PMID 37370565, 2023). "assessed the effect of two different methods of neoadjuvant therapy on the TME cells and immune markers such as CTLA-4 on 109 patients with rectal cancer." (PMID 35967381, 2022). "Another study on rectal cancer indicated that CTLA-4 expression was relatively stable after chemoradiation therapy." (PMID 28900290, 2017). "Additionally, CTLA4 gene variants have been linked to basal cell carcinoma (BCC), rectal cancer, acute kidney transplant rejection, and various inflammatory diseases." (PMID 39456732, 2024). "In addition to PD1/PDL1 targeting other immune checkpoint molecules such as cytotoxic T-lymphocyte-associated protein 4 (CTLA-4) and T cell immunoreceptor with Ig and ITIM domains (TIGIT) in combination with RT represent exciting therapeutic approaches for rectal cancer." (PMID 38623751, 2024). "Herein, we report exceptional responses observed with neoadjuvant botensilimab (BOT), an Fc-enhanced next-generation anti–CTLA-4 antibody, alongside balstilimab (BAL; an anti-PD-1 antibody) in two patients with pMMR/MSS colon and rectal cancer." (PMID 37731056, 2023).
common variable immunodeficiency (12 papers, 2019 to 2026). "CTLA4 mutation found in patients with common variable immunodeficiency leads to decreased CTLA4 protein expression in Treg cells." (PMID 41177809, 2025). "Many patients with CTLA4 gene mutations had previously been diagnosed with common variable immunodeficiency (CVID) and/or an autoimmune syndrome, however as availability of genetic diagnosis and awareness of the condition has improved the number of recognised cases has increased dramatically." (PMID 35783679, 2022). "Both LRBA and CTLA-4 were identified as causes of monogenic common variable immunodeficiency (CVID) in 2012 and 2014, respectively." (PMID 38535602, 2024). "Patients with CTLA-4 haploinsufficiency present with clinical and laboratory findings consistent with common variable immunodeficiency (CVID), autoimmune cytopenias (AIC), lymphocytic infiltration of nonlymphoid organs, and malignancy." (PMID 34248986, 2021).
HIV-1 infection (12 papers, 2009 to 2025). The type species of lentivirus and the etiologic agent of acquired immunodeficiency syndrome (AIDS). "Immune dysregulation in HIV-1 infection is associated with increased expression of inhibitory molecules such as CTLA-4, TGF-β, and IL-10." (PMID 20016783, 2009). "One potential explanation may be that the subpopulation of CD4+ T cells expressing TNF-α and CTLA-4 or PD-1 may be less readily able to support productive HIV-1 infection despite evidence that CTLA-4 signaling may be associated with increased CCR5 expression and enhanced susceptibility to infection." (PMID 22479542, 2012). "In summary, our findings suggest that in the lymph node, CTLA-4+ cells have a lower HIV-1 infection frequency compared to CTLA-4- cells, and particularly PD-1+ cells." (PMID 36776833, 2023). "In the lymph node, we found evidence that CTLA-4+ cells had a lower total HIV-1 infection frequency compared to DN cells, PD-1+ cells and DP cells, similar to our observations in the peripheral blood." (PMID 36776833, 2023). "Herein, in HIV-1NL4.3 infected Jurkat cells, miR-146a levels were gradually increased during HIV-1 infection, and the mRNA level of PD-1 and CTLA-4 were increased to a peak in day 3, and then decreased." (PMID 31827152, 2019). "Expression of cytotoxic T-lymphocyte antigen 4 (CTLA-4), a negative regulator of T-cell function, is increased in chronic HIV-1 infection." (PMID 29879143, 2018). "Upon stimulation with CD3/CD28 beads the CTLA-4 expression levels were even significantly reduced in the elderly and the role of this inhibitory receptor for the pathogenesis of HIV-1 infection in vivo remains to be elucidated." (PMID 26452480, 2015). "T-cell exhaustion is observed during HIV-1 infection; and previous reports have shown higher levels of CTLA-4 or PD-1 (protein or mRNA) on circulating CD4+ and CD8+ T-cells from HIV-1 infected patients, compared to uninfected individuals." (PMID 22276176, 2012). "The frequency of CTLA-4 positive Treg is increased in patients with chronic HIV-1 infection and is suspected to play a critical immunomodulatory role leading HIV-associated immune dysfunction." (PMID 20016783, 2009). "In addition, we found that lymph node CTLA-4+ cells have a lower HIV-1 infection frequency compared to the other cell subsets." (PMID 36776833, 2023). "An important hallmark of chronic HIV-1 infection is the immune activation, which leads to T-cell exhaustion, characterized by the persistent expression by lymphocytes of markers, such as HLA-DR, CD25, PD-1 and CTLA-4." (PMID 22276176, 2012). "An upregulated expression of various ICMs including PD-1, CTLA-4, TIM-3, LAG-3, and TIGIT has been reported in HIV-1 infection." (PMID 40872312, 2025). "Additionally, the upregulation of CTLA-4 in CD4+ T-cells was reported to cause a high level of CCR5 expression on CD4+ T-cells, thereby supporting a vigorous HIV-1 infection, which suggests that CTLA-4 upregulation by HIV infection could increase CD4+ T-cell susceptibility to HIV infection." (PMID 32967229, 2020). "CTLA-4 is upregulated in HIV-specific CD4+ T cells, particularly in patients with chronic HIV-1 infection." (PMID 20016783, 2009). "(2016) found that during untreated HIV-1 infection, T-cells expressing HIV-1 RNA and Gag protein were enriched particularly in T-cells expressing PD-1 and Tfh cell markers (PD-1+CXCR5+), with additional enrichment in cells co-expressing PD-1 with other immune checkpoint markers (TIGIT+ and CTLA-4+)." (PMID 36776833, 2023). "Intriguingly, ex vivo neutralization of miR-146a in PBMCs from chronic HIV-1 infection exhibited an elevated antiviral cytokines production as well as the expression of GZMB and perforin, while simultaneously, decreased the inhibitory receptors expression such as PD-1, CTLA-4, TIM-3 and LAG-3." (PMID 31827152, 2019).
HIV-1 infection (continued). "In agreement with this possible effect of Nef, we found that the infection frequency of intact nef was highly correlated with the HIV-1 infection frequency of DN and PD-1+ cells, but not significantly correlated with the HIV-1 infection frequency of CTLA-4+ and DP cells." (PMID 36776833, 2023).
juvenile idiopathic arthritis (12 papers, 2019 to 2025). Juvenile idiopathic arthritis (JIA) is the term used to describe a group of inflammatory articular disorders of unknown cause that begin before the age of 16 and last over 6 weeks. "It is currently used in patients with RA and juvenile idiopathic arthritis (JIA), although CTLA-4-Fc clinical efficacy is being tested on other autoimmune rheumatic diseases such as SSc." (PMID 36121543, 2022). "To date, CTLA4 Ig (abatacept), which binds to CD80/CD86 and inhibits inflammatory T cell activation, has been approved by the US Food and Drug Administration to treat RA, juvenile idiopathic arthritis, and active psoriatic arthritis." (PMID 36271469, 2022).
liver disease (12 papers, 2014 to 2025). "As a member of the immunoglobulin superfamily, CTLA-4 encodes a protein that transmits an inhibitory signal to T cells and is involved in the immune dysfunction of liver disease caused by HBV and HCC." (PMID 35847362, 2022). "So far, multiple genes have been shown to be associated with increased liver disease risk, such as CTLA-4, IL-18, transmembrane 6 superfamily member 2 and GSTM1." (PMID 34886817, 2021). "Whole exome sequencing (WES) was conducted by next-generation sequencing (NGS) in all 11 patients suffering from portal hypertension (CVID+PH), revealing a pathogenic mutation for NFKB1 in patient #3 and CTLA4 haploinsufficiency in patient #10." (PMID 38187397, 2023). "We also describe the clinical features of liver disease in some monogenic forms of PID included in the clinical spectrum of CVID as ICOS, NFKB1, NFKB2, CTLA-4, PI3Kδ pathway, ADA2, and IL21-R genetic defects." (PMID 32184784, 2020). "Interestingly, we identified a novel intronic defect in a heterozygous state (c.1066-87T>C) in a female patient with CTLA4-mediated immune dysregulation syndrome, without lung or liver disease." (PMID 38791420, 2024).
nasopharyngeal carcinoma (12 papers, 2016 to 2025). A carcinoma arising from the nasopharyngeal epithelium. "Here the authors report the results of a clinical trial of anti-PD1 (nivolumab) and anti-CTLA4 (ipilimumab) in patients with recurrent/metastatic EBV-positive nasopharyngeal carcinoma." (PMID 37188668, 2023). "A Cox regression analysis confirmed the prognostic value of the tumor CTLA-4 expression especially for the D-FFS of nasopharyngeal carcinoma patients." (PMID 28211499, 2017). "Here, we aim to evaluate the efficacy of sequential anti-CTLA-4 and anti-PD-1 treatment for recurrent or metastatic nasopharyngeal carcinoma patients (R/M NPC)." (PMID 38448521, 2024). "Moreover, considering the higher expression of PD-L1 in nasopharyngeal carcinoma, the use of PD-1 inhibitors, such as nivolumab, or a dual CTLA-4/PD-1 blockade (ipilimumab plus nivolumab) appear to be an effective strategy for the treatment of this cancer form." (PMID 35387050, 2021). "The OS, failure-free survival and distant failure free survival rate was lower in nasopharyngeal carcinoma (NPC) patients and NPC patients with high tumor CTLA-4 levels." (PMID 29682176, 2018). "The expression levels of CTLA-4 and CD28 were analyzed in 191 nasopharyngeal carcinoma (NPC) patients diagnosed and treated at our hospital between January 2010 and November 2011." (PMID 26918337, 2016).
ovarian tumor (12 papers, 2013 to 2025). "While PD-1 and CTLA-4 blockade has revolutionized treatment in some malignancies, ovarian tumors frequently deploy multiple redundant checkpoint pathways, including TIM-3, LAG-3, and TIGIT, to evade immune attack." (PMID 40643516, 2025). "Several checkpoints were coexpressed in TILs isolated from an ovarian tumor mouse model, including PD-1, CTLA-4, and lymphocyte activation gene-3 (LAG-3)." (PMID 36189283, 2022). "In this study, we show increased TIL proliferation, increased proportion of CD8+ T cells and increased TIL reactivity towards autologous tumor cell lines in vitro when CTLA-4 blockade was introduced during the initial TIL expansion from ovarian tumor fragments." (PMID 32127601, 2020). "Thus, CTLA-4 blockade of TILs during the early expansion phase improves the total numbers of TILs derived from ovarian tumor fragments." (PMID 32127601, 2020). "Recently, a study attempted to add a CTLA-4 blocking antibody during the initial TIL culture and found that CTLA-4 blockade favored the proliferation of CD8 + TIL in ovarian tumor fragments." (PMID 40369674, 2025). "The ovarian tumors showed high gene expression of LAG3 and HAVCR2 (TIM3) and enhanced levels of TIGIT and CTLA4 in recurrent tumors compared to primary tumors." (PMID 33352957, 2020). "To exploit this, we used a CTLA-4-blocking antibody, added during the initial TIL culture, and found that the blockade of CTLA-4 favored the propagation of CD8+ TILs from ovarian tumor fragments." (PMID 32127601, 2020). "used a CTLA-4 blocking antibody, which was added during initial tumor-inflating lymphocyte (TIL) culture, and found that CTLA-4 blockade favored the propagation of CD8+ TILs in ovarian tumor fragments." (PMID 38903506, 2024).
anemia (11 papers, 2012 to 2024). A reduction in the number of red blood cells, the amount of hemoglobin, and/or the volume of packed red blood cells. "Ranking profiles of s‐AEs suggested that the addition of PD‐L1 and CTLA‐4 to EP had the lowest probability of vomiting (probability 35%), anemia (33%), neutrophil (11%), and dyspnea (29%)." (PMID 36951654, 2023). "Anemia was associated with OAS1 and CTLA4 gene polymorphisms (p = 0.049 and p = 0.045, respectively), neutropenia and thromobocytopenia were associated with SOCS3 gene polymorphism (p = 0.02 and p = 0.002, respectively)." (PMID 23133602, 2012).
Chagas disease (11 papers, 2011 to 2024). A parasitic infection caused by Trypanosoma cruzi. "Comparisons of haplotype frequencies of -1722/-318/+49 polymorphisms at the CTLA-4 gene between different presentation forms of Chagas disease." (PMID 24205212, 2013). "To further understand how the ensemble of polymorphisms participates in the resistance/susceptibility to Chagas disease, we analyzed the haplotypes of SNPs observed at the CTLA-4 gene." (PMID 24205212, 2013). "Haplotype frequencies of polymorphisms at the CTLA-4 gene in patients with Chagas disease and healthy controls." (PMID 24205212, 2013). "Summary of the associations between genotypes, alleles and haplotypes of CTLA-4 polymorphisms with Chagas disease and its clinical forms, showing increased or decreased frequencies of genotypes, alleles and haplotypes." (PMID 24205212, 2013). "Comparisons of genotype and allele frequencies of polymorphisms at the CTLA-4 gene between different presentation forms of Chagas disease." (PMID 24205212, 2013). "In humans, polymorphisms at the CTLA4 gene may determine the symptoms during the chronic phase of Chagas disease; it has been shown that an increase in the expression of CTLA-4 was associated with the indeterminate form of the disease." (PMID 29209313, 2017). "Overall, alleles, genotypes and haplotypes reported to increase the expression of the regulatory molecule CTLA-4 were associated with a milder form of the disease (indeterminate), suggesting that regulatory mechanisms play a crucial role during the course of Chagas disease." (PMID 24205212, 2013). "Thus, the expression of a specific CTLA-4 haplotype can confer protection against or susceptibility to Chagas disease by modulating CTLA-4 function." (PMID 24205212, 2013). "To understand how polymorphic sites observed at genes related to immune regulation can be associated with clinical forms of Chagas disease, we firstly analyzed whether the frequencies of three polymorphisms at the CTLA-4 gene were associated with clinical features." (PMID 24205212, 2013). "This study advances the current knowledge about the immunoregulatory mechanisms mediated by CD86, CTLA-4, and by Treg cells in Chagas disease." (PMID 29599775, 2018). "The immune regulation by the host seems to be an essential factor for Chagas disease progression, and immune system inhibitory molecules such as PD-1 and CTLA-4 favor the maintenance of peripheral tolerance." (PMID 29209313, 2017). "Genotype and allele frequencies of polymorphisms at the CTLA-4 and PDCD1 genes in patients with Chagas disease and healthy controls." (PMID 24205212, 2013). "In severe chronic human infection with Trypanosoma cruzi (Chagas disease), a gradual loss of CD8+ T cells occurred, characterized by impaired cytokine production and increased inhibitory receptor expression, particularly of PD-1 and CTLA-4." (PMID 37764924, 2023). "CTLA-4 also implicated in the modulation of the immune response against T. cruzi by affecting the mechanisms that control IFN-γ and nitric oxide production during the acute phase of Chagas disease." (PMID 29599775, 2018). "None of the genotype or allele frequencies of the CTLA-4 +49A/G polymorphism showed statistically significant difference between the different clinical forms of Chagas disease and healthy controls." (PMID 24205212, 2013). "Moreover, severe/moderate cardiomyopathy patients showed lower frequency of CD4+CD25− T cells expressing CTLA-4 (P = 0.035) than free/mild cardiomyopathy patients, and Bz treated Chagas' disease patients." (PMID 22545173, 2012). "Thus, the identification if the contact cell-cell through CTLA-4 to Treg cells produces IL-10 is crucial to understanding their role in Chagas' disease." (PMID 21655351, 2011).
Chagas disease (continued). "In addition, the CTLA-4-318CT genotype is increased in the mixed form compared to cardiac and digestive groups as well as compared to controls, indicating that the CTLA-4-318T allele and the CTLA-4-318CT genotype are primarily associated with the mixed form of Chagas disease." (PMID 24205212, 2013). "When we analyzed the frequency of CTLA-4, we observed a similar proportion of this ligand on the Th1, Th2, Th17, and CD8+ Treg lymphocyte subsets of Chagas disease patients." (PMID 35665256, 2022). "The absence of the CTLA-4 -1722CC genotype in other Chagas disease variants may indicate that it can be a marker of the indeterminate form, suggesting that this genotype may protect against the development of the major chronic Chagas disease clinical manifestations." (PMID 24205212, 2013). "Many studies have demonstrated the functional role of CD80, CD86, CTLA-4, and CD28 receptors in different pathological settings, yet little is known about the role of these co-stimulatory molecules in Chagas disease patients." (PMID 30405039, 2018).